S100A1 (S100 calcium binding protein A1)
Diseases named in the same sentence as S100A1 in open-access papers (continued):
Sharing a sentence is not in itself a finding about the gene and the disease.
myocardial infarction (8 papers, 2010 to 2023). Gross necrosis of the myocardium, as a result of interruption of the blood supply to the area, as in coronary thrombosis. "Plasma S100A1 protein is a novel inflammatory biomarker associated with acute myocardial infarction and neurodegenerative disease’s pathophysiological mechanisms." (PMID 36643631, 2023). "Additionally, elevated serum S100A1 is one of the risk factors for ST-segment elevation, which is associated with cardiac function after myocardial infarction." (PMID 37217870, 2023). "In aortic coarctation and myocardial infarction models, S100A1 knockout mice have significantly higher cardiomyocyte apoptosis and more severe ventricular remodeling than wild-type mice." (PMID 37217870, 2023). "The concentration of S100A1 in plasma of patients with acute myocardial infarction increased early after infarction peaking at 8 h, and then decreased rapidly with time." (PMID 37217870, 2023). "In contrast to extracellular S100A1, which inhibits cardiomyocyte apoptosis, S100B is released into plasma after myocardial infarction and regulates apoptosis through extracellular mechanisms." (PMID 37217870, 2023). "Studies have shown that an elevated plasma S100A1 level is a significant predictor of ST-segment elevation myocardial infarction, while there is reduced S100A1 expression in failing and hypertrophic heart tissues." (PMID 34366855, 2021). "In experimental investigations with S100A1 transgenic and knockout mice, down-regulation of S100A1 protein was shown to contribute to contractile dysfunction after myocardial infarction." (PMID 26682543, 2015). "Using an anti-S100A1 antibody that was shown to prevent S100A1 internalization in CFs in vitro, we observed pro-inflammatory and pro-fibrotic effects in mice with neutralized S100A1 in experimental myocardial infarction, mirroring our in vitro results." (PMID 24833748, 2014). "Here, we investigated the role of S100A1, the S100 isoform with highest abundance in cardiomyocytes, when released from damaged cardiomyocytes during myocardial infarction (MI)." (PMID 24833748, 2014). "In the present study, we constructed a rat myocardial infarction model to investigate the temporal and spatial distribution of S100A1 in cardiomyocytes and S100A1 plasma concentrations after AMI." (PMID 23683996, 2013). "S100A1 knockout mice showed elevated systemic blood pressure, reduced endothelium-dependent vasorelaxation, and decreased survival after myocardial infarction." (PMID 20672023, 2010). "S100A1 exhibits increased expression in compensated hypertrophy, decreased expression in human cardiomyopathy, and downregulation following experimental myocardial infarction." (PMID 20672023, 2010). "Therefore, the evaluation of S100A1 is beneficial to improve clinical diagnosis and disease progression in patients with acute myocardial infarction." (PMID 37217870, 2023). "Furthermore, the knock-down of S100A1 alone significantly increased the area of myocardial infarction, the level of cardiomyocytes apoptosis, and the degree of myocardial fibrosis in IHF rats." (PMID 34366855, 2021). "In animal experiments, overexpression of S100A1 improved the cardiac function of IHF animal models, whereas a lack of S100A1 led to increased arterial pressure and mortality after myocardial infarction in mice." (PMID 34366855, 2021). "For autopsy material, all human cases of definite myocardial infarction and suspected early infarction showed well-defined areas without S100A1 staining." (PMID 23683996, 2013). "Previous studies have shown that serum S100A1 concentrations are significantly elevated after AMI and have higher sensitivity and specificity than MB and cTnI within the early hours (0–6 h) of the onset of myocardial infarction." (PMID 23683996, 2013).
glioma (7 papers, 2019 to 2025). A benign or malignant brain and spinal cord tumor that arises from glial cells (astrocytes, oligodendrocytes, ependymal cells). "S100A1 and S100B also have the ability to cause microtubule disassembly in glioma cells and myoblasts in a Ca2+-dependent manner, suggesting a possible role of S100A1 in tau pathology." (PMID 31156365, 2019). "-Ablation of S100A1 expression ↑tubulin/ microtubules levels in PC12 cells;-S100A1 causes disassembly of microtubules in U251 glioma cells and rat L6 myoblasts." (PMID 31156365, 2019). "Several known glioma markers were identified through this analysis such as Vimentin, Nestin, BCAT1, and S100A1." (PMID 35526077, 2022).
ischemia (7 papers, 2013 to 2026). A hypoperfusion of the BLOOD through an organ or tissue caused by a PATHOLOGIC CONSTRICTION or obstruction of its BLOOD VESSELS, or an absence of BLOOD CIRCULATION. "Loss of S100A1 immunoreactivity can occur within one hour of ischemia, offering one of the earliest molecular indicators of myocardial injury." (PMID 41596321, 2026). "Additional markers such as desmin disruption and S100A1 depletion further assist in identifying early ischemia." (PMID 41596321, 2026). "Inflammatory and immunohistochemical markers such as CRP, IL-6, fibronectin, desmin, complement C5b-9, and S100A1 contribute to the identification of early ischemia and myocarditis, particularly when routine histology is inconclusive." (PMID 41596321, 2026). "Given the importance of S100A1 to the regulation of eNOS activity and overall EC physiology, we set out to investigate ischemia-induced mechanisms that regulate S100A1 expression levels in ECs." (PMID 24244340, 2013). "Moreover, S100A1 plasma concentrations increased with ischemia, and reached a peak after 6 h, which was consistent with the results of IHC." (PMID 23683996, 2013).
pancreatic cancer (6 papers, 2014 to 2022).
psoriasis (6 papers, 2012 to 2024). An autoimmune condition characterized by red, well-delineated plaques with silvery scales that are usually on the extensor surfaces and scalp. "For example, S100A4 is involved in autoimmune pancreatitis, S100A11, S100A8 and S100A9 in rheumatoid arthritis, S100A1 in hypoxia-induced inflammatory response in cardiomyocytes, S100A12 in Crohn’s disease, S100A7 and S100A7A in psoriasis, S100A8, S100A9 and S100A12 in systemic lupus erythematosus." (PMID 30018736, 2018).
chromophobe renal cell carcinoma (5 papers, 2018 to 2025). Chromophobe renal cell carcinoma is a rare subtype of renal cell carcinoma, originating from the intercalating cells of the collecting ducts and macroscopically manifesting as a well-circumscribed, highly lobulated, solid tumor that is usually diagnosed at an early stage. "S100-A1 is also a diagnostic marker of intercalated cell-derived chromophobe renal cell carcinomas." (PMID 40243914, 2025). "CK7, S100A1, and parvalbumin are helpful immunohistochemical markers in the differential diagnosis between chromophobe renal cell carcinoma and TFE3/TFEB-rearranged renal cell carcinoma." (PMID 35980471, 2022). "HNF1β and S100A1 are useful biomarker for distinguishing renal oncocytoma and chromophobe renal cell carcinoma." (PMID 30466390, 2018). "Parvalbumin and CK7/S100A1 respectively are of paramount importance when TFE3/TFEB-rearranged renal cell carcinoma resembles oncocytoma and chromophobe renal cell carcinoma." (PMID 35980471, 2022). "Both tumors may express CD117, but S100A1 tends to be positive in renal oncocytoma and negative in chromophobe renal cell carcinoma." (PMID 40491617, 2025). "Expression of CK7 and parvalbumin along with the absence of S100A1 is characteristic of chromophobe renal cell carcinoma, whereas strong and diffuse labeling of S100A1 along with the under-expression of CK7 and parvalbumin are typical of TFE3/TFEB-rearranged renal cell carcinoma." (PMID 35980471, 2022).
myocardial ischemia (5 papers, 2013 to 2024). A disorder of cardiac function caused by insufficient blood flow to the muscle tissue of the heart. "Myocardial ischemia is associated with apoptosis and necrosis of cardiomyocytes, and dying cells release S100A1 into the blood." (PMID 37217870, 2023). "Recent studies on the postmortem diagnosis of myocardial ischemia have immunohistochemically examined markers that either accumulate (such as fibronectin) or leak (such as troponin, myoglobin, and S100A1) into human myocytes during ischemic injury." (PMID 38374168, 2024). "Overexpression of S100A1 has a cardioprotective effect in myocardial ischemia–reperfusion injury and can promote the recovery from global cerebral ischemia–reperfusion injury." (PMID 37217870, 2023). "Confocal microscopy revealed a significant dislocation of S100A1 from cytoplasm to cell surface during myocardial ischemia." (PMID 37217870, 2023). "Clinical origin for this study was the characterization of cardiac ischemia in humans and mice as pathological condition that entails a significant release of S100A1 from injured cardiomyocytes." (PMID 24833748, 2014). "Thus, the circulating level of S100A1 can be used as a marker for evaluating acute myocardial ischemia." (PMID 37217870, 2023). "In the present study, immunohistochemical results of the AMI animal model showed that as early as 15 min after myocardial ischemia, S100A1 depletion was detected in the subendocardial layer and papillary muscles, which was in agreement with the positively stained areas of HBFP." (PMID 23683996, 2013). "By comparing the localization changes of S100A1 subcells before and after CPB, we can predict the occurrence of myocardial reperfusion injury and prepare for the prevention of myocardial ischemia–reperfusion arrhythmia in advance." (PMID 37217870, 2023).
diabetes (4 papers, 2018 to 2021). "We detected the difference in plasma S100A1 levels between patients with and without cardiovascular risk factors, including gender, hypertension, diabetes mellitus, and smoking habit." (PMID 31523180, 2019).
endometrial carcinoma (4 papers, 2022 to 2024). A malignant tumor arising from the epithelium that lines the cavity of the uterine body.
glioblastoma (4 papers, 2023 to 2025). The most malignant astrocytic tumor (WHO grade IV). "Non-EGFRvIII samples exhibited increased expression of S100A1, a marker of mesenchymal glioblastoma, whereas EGFRvIII samples exhibited higher expression of the classic/proneural subtype marker NOTCH1 and the proneural-associated gene IDH1." (PMID 38665799, 2024).
lung carcinoma (4 papers, 2018 to 2025). "These inhibitors should undergo further preclinical and clinical trials to determine the effectiveness of targeting S100A1 in lung cancer and other solid tumors." (PMID 40090947, 2025). "Multiomics and functional studies have suggested that tumor-intrinsic S100A1 expression correlated with an immunologically “cold” TME and resistance to ICB in multiple syngeneic murine tumors and tissue samples from patients with lung cancer." (PMID 40090947, 2025). "However, the roles of S100A1, S100A3, S100A7A, S100A12, S10016, and S100G proteins in lung cancer are rarely reported." (PMID 29607329, 2018).
pulmonary arterial hypertension (4 papers, 2021 to 2025). Pulmonary arterial hypertension (PAH) is a group of diseases characterized by mean pulmonary artery pressure >20 mmHg and elevated pulmonary arterial resistance leading to right heart failure. "Deficiency of S100a1 results in pulmonary hypertension in mice due to enhanced eNOS activity and nitric oxide levels, via Akt/ERK1/2 pathways, and reduced endothelial cell survival." (PMID 34239729, 2021). "In pulmonary arterial hypertension, S100A1 mediates the HIMF-induced smooth muscle cell migration, vesicular exocytosis, and nuclear activation." (PMID 33800244, 2021). "Pigs embolized with Sephadex developed RV hypertrophy and, interestingly, showed increased RV S100A1 expression and mild pulmonary hypertension (pH)." (PMID 34239729, 2021).
renal cell carcinoma (4 papers, 2021 to 2025). "Interestingly, FYN, LRSAM1, IL20RB, CXCL11, S100A1, and MAP3K14 are also well-recognized biomarkers in the prognosis of renal cancer, which is reminiscent of the pancreatic metastasis from renal cell carcinoma in some earlier studies." (PMID 36428747, 2022). "Furthermore, S100A1 was typically positive and CK7 was usually negative regardless of the cutoff used either considering the overall MiT family translocation renal cell carcinomas or TFE3 and TFEB-rearranged renal cell carcinoma separately." (PMID 35980471, 2022).
atherosclerosis (3 papers, 2022 to 2025). A disease characterized by the build-up of fatty material and calcium deposition in the arterial wall resulting in partial or complete occlusion of the arterial lumen. "The S100 proteins S100A8, S100A9, and S100A12 play a crucial role in inflammation and atherosclerosis, while S100A1 plays a role in post-ischemic angiogenesis." (PMID 35203642, 2022).
cardiomyopathy (3 papers, 2020 to 2025). A disease of the heart muscle or myocardium proper. "This study examined the cardioprotective effects of carvedilol (CAR) and/or resveratrol (RES) and liposomal RES (LIPO-RES) against DOX-induced cardiomyopathy, pointing to their modulatory effect on oxidative stress, inflammation, S100A1 and sarco/endoplasmic reticulum calcium ATPase2a (SERCA2a)." (PMID 32079097, 2020).
chordoma (3 papers, 2019 to 2024). Chordomas are rare malignant tumors arising from embryonic remnants of the notochord in axial skeleton. "Furthermore, S100A1 is a potent diagnostic marker in clinical chordoma cases: zebrafish s100a1 was also the most significantly upregulated s100 gene in our hyperplastic zebrafish notochords, albeit under a slightly less stringent FDR threshold (logFC=2.32, P=0.006, FDR=0.096)." (PMID 31221659, 2019). "Our RNA-seq analysis of Ras-transformed zebrafish notochords mimicking activated RTK signaling revealed deregulation of clinically relevant chordoma genes, including s100a1 and bcl6 family members." (PMID 31221659, 2019). "TBXT, S100A10, and S100A1 were the pathological markers of chordoma." (PMID 36127333, 2022). "Compared with other clusters, which were considered putative malignant clusters, putative nonmalignant clusters were checked for lower gene expression levels of chordoma tumor cell markers (TBXT, S100A1, and VIM) according to the published literature 12,18,19." (PMID 36127333, 2022).
colon carcinoma (3 papers, 2018 to 2023). "This indicates that S100A1 can be a candidate biomarker for the prognosis of early-stage colon cancer." (PMID 33294444, 2020). "Although S100A1 is proved to be a biomarker in human cancers, its role in colon cancers has been rarely been studied." (PMID 33294444, 2020). "Co-immunoprecipitation was used to examine the interaction of endogenous CacyBP/SIP with S100A1 and S100A6 in colon cancer SW480 cells." (PMID 29534068, 2018).
myocardial inflammation (3 papers, 2016 to 2026). "In this study, we found that knocking down the expression of S100A1 significantly attenuated the effects of reynoutrin on improving cardiac function, cardiomyocytes apoptosis, myocardial inflammation and fibrosis, and down-regulating the expressions of MMP2, MMP9, p-p65, and TGF-β1 in rats with IHF." (PMID 34366855, 2021).
oncocytoma (3 papers, 2022 to 2024). "S100A1 is a useful marker since most oncocytomas exhibit nuclear and cytoplasmic staining, while chRCCs are usually negative." (PMID 35269747, 2022). "Other oncocytoma-specific markers are less utilized, and it could be helpful to use Ksp-cad, while S100A1 is considered as a potentially useful marker that still needs to be fully validated." (PMID 35269747, 2022).
papillary thyroid carcinoma (3 papers, 2021 to 2024). "In this report, bioinformatics analyses and immunohistochemistry assays were applied to assess the expression profile of S100A1 as well as its relationship with the pathological features and prognosis of papillary thyroid carcinoma (PTC)." (PMID 34475990, 2021). "Likewise, S100A1 is significantly upregulated in papillary thyroid carcinoma (PTC) tissues, and correlates with tumor size and lymph node metastasis." (PMID 39742274, 2024). "Inhibitor of S100A1 could also provide a new approach for treating papillary thyroid cancer." (PMID 34475990, 2021). "Recently, S100A1, a calcium-binding protein from the S100 family, was suggested to promote YAP1 activity in human papillary thyroid carcinoma cells in vitro and in vivo." (PMID 39397390, 2024). "In order to further explore the expression of S100A1 in thyroid and papillary thyroid carcinoma in humans, we collected 4 PTC tissues and paired adjacent normal thyroid tissues, and compared the expression of S100A1 protein by Western blot assays." (PMID 34475990, 2021). "In summary, our findings strongly support that S100A1 promotes papillary thyroid carcinoma cells proliferation and migration through regulating the Hippo/YAP signaling pathway, and functions as a novel biomarker for diagnosis and prognosis of papillary thyroid carcinoma." (PMID 34475990, 2021).
chronic heart failure (2 papers, 2017 to 2024). "NEW & NOTEWORTHY S100A1 is an emerging candidate for future gene-therapy treatment of human chronic heart failure." (PMID 38819384, 2024).
endothelial dysfunction (2 papers, 2022 to 2023). In vascular diseases, endothelial dysfunction is a systemic pathological state of the endothelium (the inner lining of blood vessels) and can be broadly defined as an imbalance between vasodilating and vasoconstricting substances produced by (or acting on) the endothelium. "Loss of S100A1 leads to pulmonary hypertension associated with endothelial dysfunction and endothelial cell apoptosis." (PMID 37217870, 2023). "Previously, hypoxia-induced elevation of miR-138 expression was observed in endothelial cells and was found to induce endothelial dysfunction, related to reduction in proliferation, angiogenesis, and VEGF-stimulated NO (nitric oxide) production by targeting the S100A1 gene." (PMID 35329950, 2022).
Hypertension (2 papers, 2009 to 2019). The presence of chronic increased pressure in the systemic arterial system. "Our findings showed there existed statistical significance in S100A1 levels between patients with and without hypertension or smoking history, respectively (both P < 0.05)." (PMID 31523180, 2019). "It has also been observed that the lack of S100A1 (an EF protein) expression could lead to hypertension." (PMID 19436720, 2009).
infarction (2 papers, 2013 to 2019). A localised pathological necrosis of tissue resulting from obstruction of the blood supply usually by a thrombus, an embolus, or vascular torsion. "Six hours after LAD occlusion, the depleted areas of S100A1 had further expanded with the prolongation of infarction time." (PMID 23683996, 2013). "Although the cardiac hypertrophy is a chronic process and acute release of S100A1 into bloodstream may not reflect the precise influence of plasma S100A1 level on myocardial remodeling, the results in our study still demonstrated S100A1 was a reasonable indicator of post-infarction cardiac function." (PMID 31523180, 2019).